BRAF (B-Raf proto-oncogene, serine/threonine kinase)
Diseases named in the same sentence as BRAF in open-access papers (continued):
Sharing a sentence is not in itself a finding about the gene and the disease.
melanoma (continued). "However, effects of BRAF inhibitors in melanoma brain metastases appear to be limited." (PMID 24133630, 2013). "Additionally, there are 50% of melanoma patients whose tumors do not harbor BRAF mutations and for whom no effective therapies are currently available." (PMID 23527225, 2013). "In the case of melanoma, for example, a BRAF mutation test is used to determine if a BRAF V600E mutation exists in the patient sample, and if present, that patient will receive a customized treatment with the drug Zelboraf, which is effective only for BRAFV600E-positive melanomas." (PMID 23818899, 2013). "Similarly, resistance to BRAF inhibition in melanoma has cast light on the reactivation of the MAPK pathway as a mechanism of therapeutic failure thus opening the door for the clinical use of both BRAF inhibitors and complementary inhibitors of the MAPK pathway." (PMID 23675349, 2013). "Furthermore, CD80, CD83, and CD86 expression on DC was decreased upon co-culture with melanoma cells and could be partially restored with BRAF inhibition in BRAFV600E mutant melanoma cell lines." (PMID 24194739, 2013). "Moreover, by comparing mutational changes in the pre-treatment and post-treatment cancer specimens using whole-genome sequencing, important advances in the determination of acquired drug resistance mechanisms to the BRAF inhibitor vemurafenib have been made in malignant melanoma." (PMID 23922791, 2013). "Importantly, secondary mutations in V600E BRAF have not been identified in drug-resistant tumors, thus arguing that the strategy to overcome BRAFi resistance in melanoma has to rely on the development of combinatorial approaches." (PMID 23890105, 2013). "In this study, using quantitative real-time PCR and cDNA microarray analysis, we show that the GLI1 is expressed in human melanoma cell lines and its expression is significantly higher in primary human melanoma tissues harboring BRAFV600E mutation as compared to those with wild type BRAF." (PMID 23935925, 2013). "Furthermore, there is compelling evidence that expression of V600EBRAF in primary human melanocytes causes senescence in vitro indicating that mutated BRAF alone is not sufficient for malignant transformation to melanoma." (PMID 23666755, 2013). "Interestingly, the mitochondrial oxidative phenotype has been involved in the resistance to classical chemotherapy and BRAF inhibitors in the slow-cycling subpopulation of melanoma characterized by high expression of the lysine-specific demethylase 5B (KDM5B a.k.a." (PMID 24161908, 2013). "Mutations in BRAF, c-KIT, and the ANR may be found in approximately 70% of all melanoma." (PMID 23476798, 2013). "Therefore, patients with well-controlled—BRAF wild type—systemic melanoma could possibly benefit from a brain tumour biopsy." (PMID 24455677, 2013). "Although BRAF mutation is not required for the formation of all nevi and melanomas, it is a commonly held assumption that when present, BRAF mutations are a very early mutational event that cooperates with additional alterations in growth control genes to drive melanomagenesis." (PMID 22235286, 2012). "Here, in melanocytes and in melanoma cell lines, we have studied the phosphorylation status of key PKB, mTOR and MAPK pathway components downstream of PTEN, PIK3CA, NRAS and BRAF mutations to determine whether the activity of the signalling pathways correlates with the upstream mutation." (PMID 22475322, 2012). "The concept of targeting both Raf and MEK is especially true with BRAF inhibitors and melanoma which contain mutations at BRAFV600E due to the negative feedback elicited by downstream ERK which suppresses the sensitivity of the cells to signaling induced by growth factors and Ras activity is low." (PMID 23455493, 2012). "However, clear cell sarcoma is genetically distinct lacking melanoma-associated BRAF mutations and instead harboring recurrent and characteristic chromosomal translocations involving the EWSR1 gene." (PMID 22693489, 2012).
melanoma (continued). "Similarly, the expression of the gene fusion product KIAA1549/BRAF in juvenile pilocytic astrocytoma (JPA) may be detectable in a similar manner, since another form of mutant BRAF (V600E) was found in EVs collected from plasma of melanoma patients." (PMID 22934045, 2012). "In non-small cell lung cancers sensitive to EGFR tyrosine kinase inhibition is lost usually due to ‘gatekeeper’ mutation however surprisingly acquisition of BRAF gatekeeper ‘mutations’ do not account for secondary drug resistance in melanoma that acquire resistance to BRAF inhibitors." (PMID 25562798, 2012). "Clinical trials of selective BRAF inhibitors have shown dramatic results among melanoma patients whose tumors possess BRAFV600E mutation, but not those without the mutation, highlighting the potential clinical importance of genotyping patients' tumors to select the appropriate treatment." (PMID 22235286, 2012). "Starting with a clinical case, we discuss the pathogenesis of leptomeningeal metastases and whether the leptomeninges may represent a sanctuary where melanoma cells may generate resistance and/or BRAF inhibitors cannot reach an adequate concentration for significant activity." (PMID 22594466, 2012). "Mechanisms of drug resistance in melanoma to vemurafenib do not involve mutations in BRAF itself but are associated with a variety of molecular changes including RAF1 or COT gene over expression, activating mutations in RAS or increased activation of the receptor tyrosine kinase PDGFRβ." (PMID 25562798, 2012). "Melanomas present on mucosal membranes, acral skin (soles, palms, and nail bed), and on chronic sun-induced damage areas often do not have mutations within the genes of MAP kinase pathway such as BRAF and NRAS, which are commonly mutated in intermittent sun-exposed areas." (PMID 22333219, 2012). "Sorafenib had only modest activity as a single agent in advanced melanoma and it did not appear to be more effective in the treatment of melanomas that are either WT or mutant at the BRAF gene, hence it may be targeting a kinase other than B-Raf in these melanomas (e.g., VEGFR or Raf-1)." (PMID 23085539, 2012). "Furthermore, preliminary studies suggest ipilimumab and BRAF inhibitors may also have activity in patients with melanoma brain metastases." (PMID 22640478, 2012). "Finally, polyclonality of BRAF mutations in primary melanomas indicates that BRAF mutation is not a founder event in melanomagenesis." (PMID 21224857, 2011). "Thus, reduced RND3 expression supports melanoma invasion following BRAF inhibition." (PMID 21917148, 2011). "Whether this pathway participates in melanoma invasion following BRAF inhibition is unknown." (PMID 21917148, 2011). "Interestingly, not all BRAF mutated melanoma cell lines were similarly sensitive to PLX4032 and PLX4720 though, with some cell lines exhibiting intrinsic resistance." (PMID 21505227, 2011). "The presence of a BRAF mutation, usually absent in other anal melanomas, also suggests different aetiological factors contributing to the development of this particular melanoma, with inflammatory processes and oxidative stress damage being possibly among them." (PMID 21827678, 2011). "Further support for the role for AKT signaling in intrinsic BRAF inhibitor resistance came from other studies showing that overexpression of an active form of AKT3 (myristolated AKT3) prevented apoptosis in BRAF V600E mutant melanoma cells when BRAF was inhibited." (PMID 21505227, 2011). "In addition, preclinical data had suggested that BRAFV600E mutant melanomas may continue to depend on the MAPK even after progressing on BRAF inhibitors, through the reactivation of phosphorylated ERK in resistant cells." (PMID 22194965, 2011).
melanoma (continued). "In contrast to sorafenib, recent studies of vemurafenib (PLX4032), a kinase inhibitor that specifically targets mutated BRAF, produced single-agent responses in BRAF-mutant melanoma but did not demonstrate antitumour activity in patients without an activated BRAF mutation." (PMID 21750549, 2011). "In the present study we show that the melanoma specific immunotoxin 9.2.27PE in combination with the BH-3 mimetic ABT-737, caused strong synergistic cytotoxic effect in the panel of melanoma cells, independently of their BRAF status and, as previously reported, their sensitivity to Dacarbazine." (PMID 21915275, 2011). "The BRAF proto-oncogene has recently been the focus of intensive research, as its mutation constitutively activates RAF/MEK signaling, a major driver of carcinogenesis in various malignancies, most notably in melanoma, colon cancer, and papillary thyroid cancer." (PMID 22039425, 2011). "Acquisition of a BRAF mutation is not a founder event, but may be one of the multiple clonal events in melanoma development, which is selected for during the progression." (PMID 21224857, 2011). "We demonstrated that melanoma cells heterozygous for V600E, but not V600K BRAF alleles were less sensitive to the inhibitory effect of PLX4032 and maybe be considered in patient selection and treatment." (PMID 20149136, 2010). "In human melanoma development, transformation from this benign state of cell senescence to malignancy may require additional genetic or epigenetic changes which enable BRAF to exert its oncogenic effect." (PMID 20230482, 2010). "The pro-apoptotic effects of PLX4720 were found to be BRAF specific, with high levels (>30%) of apoptosis only induced in the BRAF-V600E-mutated melanoma cell line panel (WM35, WM164 and 1205Lu), and not the NRAS-mutated melanoma cell lines (WM1346, WM1361A and WM1366)." (PMID 20531415, 2010). "Furthermore, melanoma cells, regardless of their BRAF or NRAS mutation status, are sensitive to the growth inhibitory effects of 17-AAG, consistent with the action of Hsp90 inhibitors on multiple oncoproteins, including CRAF." (PMID 21037799, 2010). "Although pre-clinical studies indicate that blocking oncogenic BRAF signalling provides a promising strategy for MM treatment, current clinical trials are yet to demonstrate whether pharmacological targeting of the BRAF/MEK/ERK pathway represents an effective treatment for melanoma as a monotherapy." (PMID 19724275, 2009). "Notably, BRAF, a downstream activator in the RAS pathway is mutated in nearly 70% of human melanoma (BRAFV600E activating mutation) while NRAS activating mutations occurs in 30% of melanomas (NRASQ61L activating mutation)." (PMID 19274086, 2009). "In addition, we identify that COX-2 expression is regulated by NFAT in BRAF-mutated melanoma cell lines, therefore highlighting that NFAT can be activated by oncogene mutation and that NFAT regulates downstream factors, which are important in melanoma biology." (PMID 19724275, 2009). "Melanomas also harbor mutations that promote the malignant phenotype, such as in BRAF, CDKN2A, PTEN, CTNNB1, NRAS, PIK3CA and KIT, but except for BRAF (∼50%) and common loss of CDKN2A, these mutations exist in a minor portion of melanoma specimens (10% or less)." (PMID 19234609, 2009). "In addition to using specific inhibitors of the pathways, we used shRNA approaches to simultaneously and specifically knock down Akt-1/2 and BRAF, resulting in synergistic/additive inhibition of melanoma cell proliferation, colony formation and invasion, as well as apoptosis." (PMID 19593429, 2009).
melanoma (continued). "However, benign nevi show similar or higher rates of the V600E BRAF mutation, and cell line and transgenic mouse models of melanoma do not clearly demonstrate the transforming power of this mutation." (PMID 19949544, 2009). "Recently, MC1R variants have been strongly associated with BRAF mutations in non-CSD melanoma, which has lead to the hypothesis that BRAF activation may be somehow indirectly induced by UV radiation." (PMID 19828018, 2009). "Confirming previously reported data, BRAF and NRAS mutations were mutually exclusive in our patients' collection; overall, BRAF or NRAS mutations were detected in 23/34 (68%) primary tumours and 24/35 (69%) lymph node metastases from the same melanoma patients." (PMID 19799798, 2009). "Therefore, the role of BRAF activation in pathogenesis of melanoma remains controversial." (PMID 19828018, 2009). "Importantly, we demonstrated that because ERK is constitutively activated in BRAF mutant melanoma cells, MITF is constantly degraded, a finding that is in agreement with the observation that MITF protein levels are generally lower in BRAF mutant melanoma cell lines than in primary melanocytes." (PMID 18628967, 2008). "Furthermore, they found a high level of IGFBP-7 expression in BRAF mutant nevi and undetectable levels in BRAF mutant melanomas, suggesting that this protein may act as a tumor-suppressor in melanoma." (PMID 19025658, 2008). "However, the role of activating BRAF mutations with respect to course and stage of melanoma is still not defined." (PMID 18631381, 2008). "Melanomas arising from skin without chronic sun damage, representing the major group of cutaneous melanomas, were shown to frequently harbour BRAF mutations, in particular the BRAF V600E mutation." (PMID 19018266, 2008). "Although this analysis is limited by its retrospective nature and the relatively small number of patients, it appears unlikely from these observations that there will be a major qualitative difference in the biological behavior between melanomas with and without BRAF mutations." (PMID 15613230, 2004). "Although this discordance among metastasis seems to contradict the observation that BRAF mutations are an early event in melanocytic nevi transformation, one possibility is that in melanomas arising from non-nevus melanocytes, BRAF mutation is a late event occurring in individual metastasis." (PMID 15613230, 2004). "Suppression of activating BRAF mutations in cultured human melanoma cells inhibited the MAPK cascade causing growth arrest and promoting apoptosis, further suggesting the potential critical role of activating BRAF mutations in malignant transformation in melanoma." (PMID 15613230, 2004). "Targeted inhibition of the MAPK pathway with BRAF and MEK inhibitors (BRAFi/MEKi) produces rapid tumor regressions in BRAF V600-mutant melanoma, yet most patients ultimately develop acquired resistance." (PMID 42196460, 2026). "Chromosome 7, with frequent copy number gains in all four cancers, harbors several key oncogenes such as EGFR, CDK6, and MET in glioma; KMT2C and PMS2 in medulloblastoma; BRAF, RAC1, and TRRAP in melanoma." (PMID 41537310, 2026). "Compared with BRAF mutant melanoma, only tunlametinib has been approved and available for clinical in NRAS mutant melanoma." (PMID 41492362, 2026). "The combination of MEK and ERK inhibitors suppresses the expression of cyclin‐D1, enhances the apoptosis, and inhibits the growth of BRAF mutant, NRAS mutant, and wild‐type melanoma." (PMID 41492362, 2026). "BRAFV600-mutant melanoma relies on hyperactivation of the MAPK/ERK pathway for tumorigenesis, with BRAF/MEK inhibitors (BRAFi/MEKi) improving patient outcomes." (PMID 41839860, 2026). "Melanoma cell lines derived from patients and induced into a mesenchymal state Via TGF-β treatment show resistance to BRAF inhibitors like vemurafenib but are sensitive to the ferroptosis inducer RSL3." (PMID 41596686, 2026).
melanoma (continued). "Another viewpoint believed that NRASmut melanoma had superior outcomes compared with the BRAFmut melanoma and NRAS/BRAF wild‐type of immunotherapy." (PMID 41492362, 2026). "We explored early signaling responses to BRAF and MAPK inhibition in a BRAFV600E-sensitive melanoma cell line and a drug-resistant ARID1A-knockout (KO) derivative." (PMID 41708984, 2026). "To quantify phenotypic adaptation in BRAFV600E-mutant melanoma, we develop a theoretical model informed by growth-rate data of WM239A-BRAFV600E cells challenged with the BRAF-inhibitor encorafenib." (PMID 41748883, 2026). "The tumours with activating BRAF mutations had a transcriptional profile more similar to cutaneous non-volar melanocytes, indicating that acral melanomas in these patients may arise from a distinct cell of origin compared with other tumours arising in these locations." (PMID 41708869, 2026). "Another example of fusion visualization in the KC is a 38-year-old female with melanoma and a TRIM33::BRAF fusion between two amplified genomic regions (TCN of 8 in an inferred diploid genome)." (PMID 41554728, 2026). "Comparing transcptomics of MRGPRX4-driven tumors shows a broad overlap with BRAF/NRAS-driven tumors; however, the MRGPRX4 model also enriches an ECM-rich, invasive neural crest-like melanoma state." (PMID 42282710, 2026). "NCT03149029 investigating the sequence of BRAF–MEK inhibitor (trametinib with dabrafenib) and anti‐PD‐1 (pembrolizumab) in BRAFmut melanoma." (PMID 41492362, 2026). "This study offers important insights into the research on BRAF and MEK inhibitor resistance in melanoma, but certain limitations should be noted." (PMID 39897423, 2025). "Significant growth inhibition was observed in nearly all melanoma cell lines after exposure to LY3009120, suggesting its value for further in vitro and in vivo testing to target BRAF-resistant tumors and to study resistance mechanisms in comparative oncology." (PMID 40563676, 2025). "In BRAF-mutant MM27 PDX xenografts, the combination of domatinostat with the USP7 inhibitor P5091 was well-tolerated and inhibited melanoma growth accompanied by apoptosis induction and reduction of senescent cell numbers in the tumors." (PMID 39935431, 2025). "Noteworthy, in immunodeficient GSDMD-positive mice, the BRAF-MEK inhibitor is unable to induce pyroptosis and subsequent elimination processes of melanoma." (PMID 41291696, 2025). "Top 10 most frequent and central keywords in BRAF and MEK inhibitor resistance research in melanoma." (PMID 39897423, 2025). "In fact, the study revealed that CK2α overexpression sustains ERK activity, even in the presence of BRAF and MEK inhibitors, by promoting melanoma progression and therapeutic resistance." (PMID 40508214, 2025). "This bibliometric analysis provides valuable insights into the global research landscape of BRAF and MEK inhibitor resistance in melanoma, offering a comprehensive understanding of key contributors, research trends, and emerging therapeutic strategies." (PMID 39897423, 2025). "Medical records from six centers were reviewed for adults with BRAF V600E/K–positive, completely resected Stage III melanoma who received at least 12 months of adjuvant dabrafenib plus trametinib." (PMID 40366077, 2025). "FRA1 also contributes to therapy resistance in melanoma, with elevated FRA1 levels observed in BRAF inhibitor-resistant cells." (PMID 41286309, 2025). "Previous studies have identified several molecular drivers of melanoma that affect aerobic glycolysis and OXPHOS, as well as the expression levels of peroxisome proliferator-activated receptor-γ coactivator-1α (PGC-1α), BRAF, and NRAS." (PMID 40404919, 2025). "Together, these findings underscore the dynamic nature of the research landscape and point to critical areas of focus for future studies on BRAF and MEK inhibitor resistance in melanoma." (PMID 39897423, 2025).